DIS3L (DIS3 like exosome 3'-5' exoribonuclease)
Description:
Catalytic component of the RNA exosome complex which has 3'->5' exoribonuclease activity and participates in a multitude of cellular RNA processing and degradation events. In the cytoplasm, the RNA exosome complex is involved in general mRNA turnover and specifically degrades inherently unstable mRNAs containing AU-rich elements (AREs) within their 3' untranslated regions, and in RNA surveillance pathways, preventing translation of aberrant mRNAs. It seems to be involved in degradation of histone mRNA.
Synonyms: DIS3L1; KIAA1955; MGC4562; FLJ38088
Tractability: Antibody: its Gene Ontology location is reachable by antibodies, with high confidence; the Human Protein Atlas places it where antibodies can reach. PROTAC: ubiquitination databases record sites on it; its protein half-life has been measured.
Gene: Protein-coding gene on chromosome 15 (66,293,217 to 66,333,898, forward strand). Ensembl gene ENSG00000166938.
Subcellular location: Cytoplasm
Subcellular location (Human Protein Atlas): Basal body; Centrosome; Cytosol; Plasma membrane
Gene Ontology:
Molecular function: 3'-5'-RNA exonuclease activity; enzyme binding; exoribonuclease II activity; protein binding; RNA binding; RNA nuclease activity
Biological process: RNA catabolic process; RNA processing; rRNA catabolic process; mRNA catabolic process; gene expression
Cellular component: cytoplasm; cytoplasmic exosome (RNase complex); cytosol; exosome (RNase complex)
Genetic constraint (gnomAD): Loss-of-function variants: 97 observed, 119.13 expected, observed/expected ratio (o/e) 0.81, 90% interval 0.69 to 0.96. The upper end of that interval is the gene's LOEUF score, 0.96, which puts it in group 4 of 6, group 1 being the genes least tolerant of losing a copy. Missense variants: 1,191 observed, 1,329.1 expected, observed/expected ratio (o/e) 0.9, 90% interval 0.85 to 0.94. Synonymous variants: 426 observed, 473.48 expected, observed/expected ratio (o/e) 0.9, 90% interval 0.83 to 0.98.
Homologues: Orthologues: chimpanzee DIS3L (99% identical), macaque DIS3L (98% identical), dog DIS3L (93% identical), pig DIS3L (92% identical), mouse Dis3l (92% identical), rat Dis3l (91% identical), guinea pig DIS3L (87% identical), tropical clawed frog dis3l (68% identical), zebrafish dis3l (63% identical), rabbit DIS3L (54% identical). Paralogues in human: DIS3 (33% identical), DIS3L2 (23% identical).
Diseases named in the same sentence as DIS3L in open-access papers:
DIS3L is named in the same sentence as 10 diseases in open-access papers, as found by Europe PMC text mining. Sharing a sentence is not in itself a finding about the gene and the disease. The quoted sentences say what the papers report.
colonic adenomas (1 paper, 2023). "ElaC ribonuclease Z 2 (ELAC2) is primarily associated with prostate cancer, and MARCH6, along with ACSM2B, DEF8, DIS3L, and KCNA5 gene variants, have not been associated with colonic adenomas yet." (PMID 36765865, 2023).
medulloblastoma (1 paper, 2021). A malignant, invasive embryonal neoplasm arising from the cerebellum. "Additionally, a knockdown of DIS3L consistently inhibited cell growth in human medulloblastoma." (PMID 34072580, 2021).
myeloma (1 paper, 2015). "It is useful to note that there appears to be an accumulation of mutations in the RNB domain of DIS3 but not DIS3L in myeloma, suggesting that inhibition specifically of the exonucleolytic activity of the nuclear exosome is what may facilitate oncogenesis." (PMID 26193331, 2015).
myocardial infarction (1 paper, 2019). Gross necrosis of the myocardium, as a result of interruption of the blood supply to the area, as in coronary thrombosis. "When subsetting the statistical tests by MAF range, BTH uncovers six associations, including a locus regulating variance of the gene DIS3L, recently identified as a possible risk factor for myocardial infarction, and a locus regulating the variance of the gene MAP2K1, involved in cardiac signaling." (PMID 29982387, 2019).
ovarian carcinoma (1 paper, 2021). A malignant neoplasm originating from the surface ovarian epithelium. "In addition, several other potentially interesting targets of YTHDF2 in ovarian cancer have been identified, such as the putative tumor suppressors TRERF1, ZDHHC14, DIS3L, Vps18, NOD1, and SLC9A8." (PMID 33658012, 2021).
ulcer (1 paper, 2025). "However, our clinical sample validation did not demonstrate the significant differential expression of DIS3L, possibly due to its limited expression in ulcer tissues." (PMID 40722759, 2025).
cancer (2 papers, 2021 to 2024). A tumor composed of atypical neoplastic, often pleomorphic cells that invade other tissues. "For SETD4 and DIS3L, where the ΔuAUG variants caused enhanced translation of the downstream CDS, ectopic overexpression of the related proteins has previously been linked to several types of human cancer and was associated with poor overall survival." (PMID 34072580, 2021).
DIS3L also shares sentences with these, for which no sentence is quoted: tumor (2 papers); adenoma (1); prostate carcinoma (1).